FTO (FTO alpha-ketoglutarate dependent dioxygenase)
Diseases named in the same sentence as FTO in open-access papers (continued):
Sharing a sentence is not in itself a finding about the gene and the disease.
Obesity (continued). "In an investigation that was comprised of 788 unrelated Mexican-Mestizo individuals, the FTO SNPs (rs9939609, rs1421085, and rs17817449) were a major risk factor for obesity." (PMID 31477138, 2019). "This field was reignited in 2011, following the discovery of the m6A demethylase FTO (fat mass and obesity-associated protein), a protein involved in human obesity, as a so-called ’eraser‘ enzyme that removes m6As present on mRNAs." (PMID 30650668, 2019). "Variations in the fat mass and obesity-associated (FTO) gene (16q12.2) are associated with obesity in some populations." (PMID 31810473, 2019). "FTO is originally considered as a body mass and obesity associated gene, which mainly serves as a metabolic regulator." (PMID 31827395, 2019). "Of the 47 compliant subjects, 15 were of normal risk for obesity whereas 32 were carriers of the risk alleles for the FTO gene." (PMID 31477138, 2019). "To date, the fat mass and obesity-associated (FTO) gene has been identified as the strongest common genetic predictor of obesity." (PMID 31516636, 2019). "Here, we demonstrate that fat mass and obesity associated (FTO), as an m6A demethylase, plays a critical anti‐tumorigenic role in clear cell renal cell carcinoma (ccRCC)." (PMID 30648791, 2019). "Fat mass (FM) and obesity-associated FTO is the first obesity risk gene recognised by genome wide association studies (GWAS) and is the gene most strongly associated with an increase in BMI." (PMID 30759834, 2019). "Different polymorphisms of the FTO (fat-mass and obesity-associated) gene have been consistently associated with obesity." (PMID 31007685, 2019). "This disruption leads to an autonomous developmental shift from beige energy-producing to white energy-storing adipocytes, which can explain the obesity-associated phenotypes observed in FTO risk variant(s)." (PMID 31482095, 2019). "In 2007 a genome-wide association study (GWAS) found a single nucleotide polymorphism (SNP) in the fat mass obesity (FTO) gene to be associated with increased BMI in both children and adults." (PMID 31836807, 2019). "In support of this, in a previous study conducted in a South Indian population (CURES), the FTO SNP, rs8050136, was associated with an increased risk of obesity." (PMID 31516636, 2019). "The latest evidence indicated the association between rs9939609 of FTO (p = 0.026) and obesity (BMI ≥ 30 kg/m2) in 1188 Taiwanese subjects." (PMID 31852448, 2019). "The most notable genetic variants from FTO associated with obesity and body composition traits are a cluster of at least 20 common SNPs from its first intron." (PMID 32076432, 2019). "Here we found that the obesity-associated protein FTO, also an m6A eraser, plays an important role in melanoma." (PMID 31239444, 2019). "The findings suggested that minor allele carriers of FTO rs8050136 who consumed high carbohydrate had higher risk of developing obesity traits." (PMID 31024458, 2019). "It seems that genes related to obesity pathology (FTO, ADIPOQ, and MC4R), in genomic research association, are related to metabolic aspects and BMI in PCOS patients." (PMID 32133054, 2019). "Fat mass and obesity-associated (FTO) variant rs9939609 was the first locus to be positively associated with obesity-related phenotypes." (PMID 29679223, 2018). "Polymorphisms of FTO and adiponectin genes can be used (in addition to age and BMI at time of diagnosis) in the model of obesity prediction after breast cancer treatment." (PMID 29675043, 2018). "rs7195994 is in LD with rs2540767 (r2 = 0.9), which shows chromatin interaction with the IRX3 gene, which some studies have suggested is one of the causal genes for obesity/BMI at the FTO locus." (PMID 30166627, 2018). "The FTO gene encodes a 2-oxoglutarate-dependent nucleic acid demethylase and various studies have reported that variants in the FTO locus are strongly linked with obesity and can predict risk of T2D and cardiovascular disease." (PMID 30564199, 2018).
Obesity (continued). "Meta-analysis studies have validated and confirmed that the influence of FTO variants on obesity risk is attenuated through physical activities as well as dietary and drug-based interventions, although the underlying mechanism remains elusive." (PMID 30105001, 2018). "FTO, a demethylase which regulates 6-methyladenosine modifications of mRNAs, has also been linked to increased risk for obesity and type 2 diabetes." (PMID 29490708, 2018). "Our results showed a higher prevalence of the FTO genotype in students with the risk allele (A) for obesity (57.5%)." (PMID 30254759, 2018). "This study aimed to investigate the association of the fat-mass and obesity-associated gene (FTO) rs9939609 variant with T2DM and body mass index (BMI) among Palestinian population." (PMID 30170548, 2018). "Since the obesity-associated SNPs are on the intron 1 region of the FTO gene, the mechanisms through which they influence body mass are uncertain." (PMID 30124167, 2018). "In populations of different ancestry such as African Asian, South Asian, Caucasian and Pima Genetic, predisposition to, for instance, the FTO gene is confirmed to predispose for obesity." (PMID 29274011, 2018). "For instance, investigations of the well-known obesity gene, FTO, have demonstrated that polymorphisms in intronic regions can have long reaching effects on genes." (PMID 30026463, 2018). "Leptin (LEP) and fat mass and obesity-associated (FTO) alleles are known to influence body fat mass in humans, potentially via effects on appetite." (PMID 30241328, 2018). "FTO was the first obesity-susceptibility gene identified through GWAS and continues to be the locus with the largest effect on BMI and obesity risk." (PMID 29161441, 2018). "Studies have demonstrated that a strong association exists between FTO SNPs and/or overweight/obesity with the increased risk of various types of cancers, implying a role of FTO in the pathogenesis of cancers." (PMID 30105001, 2018). "For example, polymorphism in the FTO gene are the strongest GWAS signals for obesity, but the functional mechanism of the association appears chiefly due to the effects of the SNPs on two neighbouring genes, IRX3 and RPGRIP1L37." (PMID 29955040, 2018). "Single nucleotide polymorphisms (SNPs) in intron 1 of FTO have been associated consistently with obesity risk across different ages and populations." (PMID 29686893, 2018). "Although variants in the FTO gene are unequivocally associated with obesity and type 2 diabetes, the biological function of FTO itself is not fully understood." (PMID 30388740, 2018). "A meta-analysis of 12 studies including 5000 obese and 9853 controls showed a strong association of the FTO rs9939609 polymorphism with obesity among children and adolescents from several Caucasian populations." (PMID 29343214, 2018). "A haplotype in the first intron of the FTO gene had a strong association with obesity indices in adolescent boys after adjustments for calorie intake and physical activity." (PMID 30126381, 2018). "This is in concordance with many other studies conducted in the Asian and European populations that strongly linked the FTO rs9939609 SNP to obesity susceptibility, with the ‘T’ allele indicating a protective role." (PMID 29343214, 2018). "High-fat diet-induced obesity is attenuated and exaggerated in FTO-deficient mice and transgenic mice overexpressing FTO, respectively." (PMID 30388740, 2018). "Some of the obesity-associated FTO SNPs, in particular rs9939609 and rs8050136, have also been associated with T2D." (PMID 29410390, 2018). "This modification is established by the METTL3 - METTL14 heterodimer and erased by FTO (fat mass and obesity-associated) and ALKBH5, two demethylases belonging to the 2-OGDD superfamily." (PMID 30319972, 2018). "The recent discovery of FTO acting as an m6A eraser paved a novel way to reveal the molecular mechanism that links FTO with the increased susceptibility to overweight and obesity." (PMID 30105001, 2018).
Obesity (continued). "A study in 2013 showed that the FTO obesity-risk allele (rs9939609 T/A) is associated with increased FTO expression, reduced m6A ghrelin mRNA methylation, and increased ghrelin expression." (PMID 30105001, 2018). "FTO variants have been associated in diverse ancestries with obesity-related traits, as well as alcohol consumption and alcohol dependency." (PMID 29912962, 2018). "The common rs17782313 MC4R gene polymorphism was associated with obesity in both European adults and children showing a synergistic effect with FTO gene on obese phenotype." (PMID 30338250, 2018). "There is also evidence suggesting a variant of the fat mass and obesity-associated (FTO) gene affects brain structure, causing deficits in the frontal and occipital lobes." (PMID 28943197, 2018). "The FTO gene, particularly the rs9939609 variant, is the most well studied gene globally that has been implicated for its role in obesity development." (PMID 29343214, 2018). "In mice, the loss of the FTO gene caused post-natal growth retardation, and FTO overexpression led to increased food intake and obesity." (PMID 29769081, 2018). "A single nucleotide polymorphism (SNP) in the fat mass and obesity-associated (FTO) gene is a strong predictor of obesity in humans." (PMID 30124167, 2018). "Our results show that there was a significant association between the FTO rs9939609 genotype and obesity, where the homozygous mutant AA genotype predisposed individuals to increased BMI." (PMID 29343214, 2018). "Polymorphisms within the fat-mass and obesity-associated gene (FTO) are of particular interest as they have known effect on obesity which is a major risk factor for T2DM." (PMID 30170548, 2018). "The fat mass and obesity-associated gene (FTO) was the first common variant identified by genome-wide association studies that influences obesity risk." (PMID 29686893, 2018). "FTO encodes a 2-Oxoglutarate–Dependent Nucleic Acid Demethylase and is associated with obesity and Body Mass Index (BMI)." (PMID 30166627, 2018). "The FTO gene rs9939609 polymorphism shows correlations with body mass index (BMI), overweight, obesity, and other risk factors of cardiovascular disease." (PMID 29675043, 2018). "A paradigm is the fat mass and obesity-associated protein (FTO) gene: as the name indicates, single nucleotide polymorphisms (SNPs) identified in this gene have been associated with obesity and type 2 diabetes risk." (PMID 30018554, 2018). "Common genetic variants of the fat mass and obesity associated (FTO) gene are strongly associated with obesity and type 2 diabetes." (PMID 30388740, 2018). "Several studies have demonstrated, through self-reported questionnaires and objective physical activity devices, that obesity-related traits associated with FTO risk alleles are attenuated in individuals with higher physical activity levels." (PMID 29686893, 2018). "The FTO gene rs9939609 polymorphism is associated with body mass and risk of overweight and obesity in Polish children, as well as in the Podlaskie Province." (PMID 29675043, 2018). "In recent years, the most commonly analyzed genetic factor is the fat-mass and obesity-associated (FTO) gene." (PMID 29675043, 2018). "Using a whole-exome sequencing filtering pipeline one candidate gene [fat mass and obesity–associated gene (FTO)] was identified." (PMID 29161441, 2018). "We also conducted a leave-one-out analysis, which showed that the SNP with the largest contribution to the effect is rs1421085 located on chromosome 16 in the second intron of the FTO (fat mass and obesity associated) gene." (PMID 30254091, 2018). "Two of these genes are the Vitamin D receptor (VDR) gene and the fat mass and obesity associated (FTO) gene." (PMID 29343214, 2018). "The rs9939609 polymorphism of the human fat mass and obesity associated (FTO) gene was the first robust identification of a common gene variant to be associated with increased body mass index (BMI) and obesity." (PMID 30356143, 2018).
Obesity (continued). "Some of them demonstrated that the FTO polymorphisms are related to body mass index (BMI) and obesity, and strongly contribute to MetS-related abnormalities." (PMID 29315078, 2018). "The rs9939609 FTO gene polymorphism was associated with certain obesity complications, such as high blood pressure, percentage body fat and fat mass, plasma insulin levels, and insulin resistance." (PMID 30338250, 2018). "Evidence for individual genotype-by-environment interactions in human cohort studies is very sparse, despite the well-known example of the largest risk factor for obesity, the FTO locus, robustly shown to have a stronger influence as BMI increases." (PMID 30110940, 2018). "The fatmass- and obesity-associated gene (FTO) was the first geneassociated to obesity in genome-wide association studies (GWAS)." (PMID 29870569, 2018). "Although the relationship between FTO genetic variant and obesity-related traits (BMI, obesity risk, waist circumference, body fat mass) has been confirmed in several populations, the physiological function of this gene in body weight regulation seems unclear." (PMID 29795275, 2018). "For example, it is suggested that the obesity-associated (FTO) gene levels in the liver are involved in oxidative stress and lipid deposition, which characterize NAFLD." (PMID 29850450, 2018). "Some patients were carriers of polymorphisms PLIN4 -11482G > A-, fat mass and obesity-associated (FTO) -rs9939609 A/T- and β-adrenergic receptor 3 (ADRB3) -Trp64Arg." (PMID 29361938, 2018). "The possible association of the rs9939609 polymorphism of FTO gene with the development of obesity was also investigated." (PMID 30356143, 2018). "Since then, several studies represent various ethnic populations, confirmed strong associations of the FTO rs9939609 with obesity." (PMID 30170548, 2018). "The most compelling evidence of genetic involvement is the fat mass and obesity-associated FTO gene located within the chromosome 16q12.2 region, and expressed mainly in the hypothalamus." (PMID 30241328, 2018). "Fat mass and obesity-associated protein (FTO) single-nucleotide polymorphisms (SNPs) have been linked to increased body mass and obesity in humans by genome-wide association studies (GWAS) since 2007." (PMID 30105001, 2018). "It is possible that the obesity-associated SNPs lead to increased expression of FTO, which in turn contributes (at least to some extent) to an increased susceptibility to overweight and obese, as well as an increased risk of cancer development." (PMID 30105001, 2018). "The FTO gene polymorphism is associated with an increase in the risk of obesity, as well as type 2 diabetes, heart failure, coronary heart disease, lifetime all-cause and ischemic stroke, hypertension, dyslipidemia, metabolic syndrome, and mortality." (PMID 30111348, 2018). "One example of such a gene–environment interaction is the interaction between the obesity variants of FTO and physical activity." (PMID 29942512, 2018). "A genome-wide association study has identified common variants in the fat mass and obesity associated (FTO) gene to be associated with obesity and type 2 diabetes." (PMID 30388740, 2018). "Fat mass and obesity related gene (FTO), located at 16q12.2, is associated with obesity and type 2 diabetes mellitus (T2DM)." (PMID 29764479, 2018). "The consensus of evidence suggests that FTO risk alleles are associated with elevated body weight across different ages and populations, with each minor risk allele increasing BMI and obesity risk by 0.25–0.39 kg·m−2 and 1.18–1.27 fold, respectively." (PMID 29686893, 2018). "FTO (Fat mass and obesity associated gene; rs9939609), FSHB (Follicle stimulating hormone beta subunit; rs6169), FSHR (Follicle stimulating hormone receptor; rs6165/rs6166), and INSR (Insulin receptor; rs1799817) genes were genotyped using HRM assay." (PMID 30596735, 2018).
Obesity (continued). "The significant association between energy intake and CLOCK, a regulatory gene in the circadian system, as well as FTO, an obesity-associated gene, were reported to increase total energy intake by candidate gene association studies." (PMID 30071075, 2018). "A haplotype in the first intron of the FTO gene had a strong association with obesity indices in Iranian adolescent males." (PMID 29677190, 2018). "FTO (fat mass- and obesity-associated) is the most investigated gene in obesity and has complex molecular mechanisms that are yet to be elucidated." (PMID 29321599, 2018). "One of the first published studies using the UKT2DGCC found an association in the FTO gene with obesity." (PMID 29025058, 2018). "Studies have examined the effect of FTO variants on regulators of energy homeostasis to elucidate the mechanisms influencing FTO-mediated obesity risk." (PMID 29686893, 2018). "Obesity is a multifactorial disease influenced by several genetic factors, including the fat mass and obesity-associated (FTO) gene, which is expressed in the whole organism, mainly in hypothalamus, and thus associated with energy balance regulation." (PMID 29854435, 2018). "Strongly linked with the development of obesity, the fat mass and obesity-associated (FTO) gene was one of the first genetic loci identified as being associated with body weight." (PMID 29484031, 2018). "A signal of the fat mass and obesity-associated (FTO) gene had been reported in a genome-wide association study of osteoarthritis." (PMID 29606151, 2018). "Genetic studies have showed variants in FTO are associated with an increased body mass index (BMI) which is an obesity-related measurement in several studies." (PMID 29606151, 2018). "The study proved a positive association between AA genotype of the rs9939609 FTO gene polymorphism and the risk of overweight/obesity." (PMID 30338250, 2018). "The fat mass and obesity associated (FTO) gene, one of the first obesity-genes ever identified, remains nonetheless one of the most strongly associated with obesity." (PMID 29520227, 2018). "This mini review discusses the roles and underlying molecular mechanisms of FTO in both obesity and cancers, and also summarizes recent advances in the development of FTO inhibitors." (PMID 30105001, 2018). "Variation in the fat mass and obesity-associated gene (FTO) has been associated with susceptibility to obesity, but the association appears to be modified by diet." (PMID 29484031, 2018). "An altered activity of such receptors, highly expressed in reward-related regions, has been reported in carriers of obesity-risk alleles of the fat mass and obesity associated (FTO) gene." (PMID 29520227, 2018). "But surprisingly, subsequent investigations revealed that the obesity-associated, non-coding region within the FTO gene actually serves as an enhancer element for the IRX3 gene through long-range chromatin interactions with its promoter." (PMID 29914202, 2018). "A recent large meta-analysis examining genome-wide and PA interaction in obesity found that the effect of obesity risk loci of fat mass and obesity-associated (FTO) gene was attenuated by 30% in physically active individuals." (PMID 29755414, 2018). "Epidemiology studies also showed a strong association of FTO SNPs and overweight/obesity with increased risk of various types of cancers." (PMID 30105001, 2018). "The fat mass and obesity-associated (FTO) gene encodes a 2-oxoglutarate-dependent nucleic acid demethylase." (PMID 29606151, 2018). "Genetic studies have repeatedly reported the association between a common variant in the fat mass and obesity-associated (FTO) SNP rs9939609 and increased BMI18–21." (PMID 29531329, 2018). "Previous neuroimaging studies observed altered brain responses to food stimuli in individuals with rare monogenic forms of hyperphagia and obesity, and in carriers of risk alleles of genes associated with common obesity, such as the FTO-gene." (PMID 28597337, 2018).